FH (fumarate hydratase)
Diseases named in the same sentence as FH in open-access papers (continued):
Sharing a sentence is not in itself a finding about the gene and the disease.
renal carcinoma (continued). "Then, taking advantage of the data from The Genome Cancer Atlas (TGCA), we found that FH loss resulted in hypermethylation and suppression of miR-200 in a larger cohort of FH-deficient renal cancers." (PMID 27886164, 2017). "Mutations in the tricarboxylic acid (TCA) cycle enzyme fumarate hydratase (FH) are associated with a highly malignant form of renal cancer." (PMID 25613188, 2015). "Loss-of-function mutations in the tumor suppressor gene fumarate hydratase (FH) predispose to an aggressive type of renal cancer." (PMID 23499446, 2013). "FH mutations have primarily been linked to papillary type II renal cancer, a histologic variant that accounts for less than 10% of all renal cancers." (PMID 21695080, 2011). "Notably, individuals with germline mutations in fumarate hydratase (FH) face a heightened risk of aggressive renal cancer, for which effective treatment options are scarce." (PMID 40253354, 2025). "Similarly, in a subset of renal cancers associated with fumarate hydratase (FH) mutations, accumulated fumarate modifies KEAP1 thiols, further enhancing NRF2 activity." (PMID 40394395, 2025). "Additionally, research has investigated the sensitivity of FH-deficient renal cancer cells to oxidative stress." (PMID 40253354, 2025). "Interestingly, the loss of function of fumarate hydratase (FH), a tumor suppressor gene in renal cancer, was found to promote ferroptosis resistance." (PMID 35065965, 2022). "Although germline mutations of FH loss predispose to renal cancer in patients with HLRCC, it is still unclear whether additional oncogenic events are required to transform Fh1-deficient cells." (PMID 36269833, 2022). "However, FH expression is often upregulated in tumor cells, including renal cancer and AML cells, which can be explained as FH mutation and dysfunction and needs further investigation." (PMID 34784264, 2022). "In addition, loss of fumarate hydratase (FH) is associated with an EMT signature via the suppression of miR-200 in patients suffering from renal cancer." (PMID 34768768, 2021). "The FH mutation of mitochondrial enzyme induces enhanced carcinogenic risk in renal carcinoma and leiomyosarcoma, SDH mutation induces carcinoma in neuroblastoma, and IDH causes malignant cancers like glioma, myeloid neoplasia, chondrosarcoma, and cholangiocarcinoma." (PMID 34717757, 2021). "FH mutations predispose to a highly aggressive and metastatic form of renal cancer." (PMID 27886164, 2017). "Fumarate hydratase (FH) mutations are associated with renal cancer." (PMID 25613188, 2015). "Indeed, it was initially thought that the stabilization of the transcription factor hypoxia-inducible factor (HIF), caused by the accumulation of fumarate, played a key role in the tumorigenesis of FH-deficient renal cancer." (PMID 24280230, 2013). "In xenograft models, an 8-week treatment with vandetanib substantially increased tumor-free survival to 13 months, indicating that ABL1 inhibition could be a viable clinical strategy for managing aggressive FH-deficient renal cancers and other glycolysis- and oxidative stress-driven tumors." (PMID 40253354, 2025). "This single-site retrospective study included patients with histologically confirmed FH-RCC or with a renal cancer and known germline FH mutation; imaging of the renal mass before treatment with contrast-enhanced CT, contrast-enhanced MRI, or FDG PET/CT between October 2007 and May 2019." (PMID 33608050, 2021). "Indeed, it was described that fumarate accumulation drives EMT transformation in kidney epithelial cells, through the inhibition of miR200ba429, thus promoting renal carcinomas formation in both FH deficient HLRCC and FH proficient cells treated with exogenous fumarate." (PMID 33233657, 2020). "Therefore, FH deficiency may lead to epigenetic reprogramming in different cancers, as gastrointestinal stromal tumors and renal cancer, characterized by FH mutations." (PMID 31881713, 2019).
renal carcinoma (continued). "However, it appears that other genetic or environmental factors might be involved in causing an increase of susceptibility to renal cancer in addition to FH mutation." (PMID 23203078, 2012). "Fumarate hydratase deficiency is the hallmark of a genetic form of renal carcinoma, HLRCC, characterised by heterozygous FH deletion." (PMID 40721560, 2025). "The molecularly defined renal carcinomas include TFE3-rearranged RCC, TFEB-altered RCC, ELOC-mutated RCC, FH-deficient and SDH-deficient RCC, ALK-rearranged RCC, and SMARCB1-deficient renal medullary carcinomas." (PMID 38235567, 2024). "Although renal cancer as an early manifestation of HLRCC was less frequent as reported, an appropriate surveillance strategy is enormously necessary for carriers of FH mutations." (PMID 36981015, 2023). "FH has been reported to alter cancer cell migratory potential, and hopefully as a therapeutic target in renal cancer." (PMID 34737838, 2021). "For example, by microarray analysis, one confirmed that fumarate hydratase messenger RNA (TCA cycle II pathway) was low expression in renal cancer cells." (PMID 31258820, 2019). "HO-1 enables renal carcinoma cells with a defect in fumarate hydratase to proliferate despite the defect in the tricarboxylic acid cycle." (PMID 28978042, 2017). "We then analyzed two panels of isogenic FH-deficient lines; FH1KOMEFs reconstituted with either FH or FHcyt and UOK262 (derived from a metastasis from an FH mutant renal cancer, which we have genetically complemented with the same FH or FHcyt constructs." (PMID 23643539, 2013). "However, VHL mutations have also been described in several other subtypes of renal cancer; for instance, tubulocystic RCC (TC-RCC) (17%), papillary RCC (papRCC) (1.1%), chrRCC (1.5%), and FH-deficient RCC (1.8%)." (PMID 37999735, 2024). "Although our patient tested negative for 19 genes known to cause renal cancer syndromes, including FH, VHL, FLCN, and MET, the possibility that the patient has a coexisting autosomal dominant renal cancer syndrome is unlikely but cannot be excluded." (PMID 38802873, 2024). "This role may be particularly relevant to the pathogenesis and treatment of diseases associated with reduced FH levels, such as Systemic Lupus Erythematosus (SLE) and FH-deficient renal carcinoma." (PMID 38185636, 2024). "FH functions as a tumor suppressor in lyomeioma and renal kidney cancer." (PMID 37016705, 2023). "FH loss predisposes to hereditary leiomyomatosis and renal cell carcinoma (HLRCC), a cancer syndrome characterized by the presence of benign tumors of the skin and uterus and a highly aggressive form of renal cancer." (PMID 36269833, 2022). "In addition, germline loss-of-function mutations of the TCA cycle enzyme genes, including FH, SDHB, SDHC, and SDHD, have been identified in renal cancers that appear to have an increased risk for more aggressive tumors." (PMID 34609963, 2021). "In order to test whether this could be extended to HLRCC, the metabolic profile of spent media of the patient-derived FH-deficient renal cancer cell line UOK262, indicated hereafter as UOK, was compared to FH-reconstituted UOK cells (UOKpFH)." (PMID 24280230, 2013). "Together with the fact that FH loss-of-function is associated with renal cancer, these observations indicate that kidney cells may better survive the loss of the TCA cycle enzyme FH." (PMID 24280230, 2013). "Finally, we demonstrate that overexpression of FH in renal cancer cells inhibits cellular migration and invasion." (PMID 21695080, 2011). "It is not yet clear how the loss of FH predisposes patients to renal cancer." (PMID 24280230, 2013). "Mutations and loss of function of certain metabolic enzymes (fumarate hydratase — FH and succinate dehydrogenase — SDH) in the tricarboxylic acid (TCA) cycle are described as precursors of rare inherited and renal cancers." (PMID 35029792, 2021).
renal carcinoma (continued). "Fumarate hydratase inactivation results in fumarate accumulation, succination of the KEAP1 cysteine residues, and NRF2 activation in renal carcinomas." (PMID 31267557, 2019). "Furthermore, they may indicate that in human FH-deficient renal cancer, the lack of p16 induction may help avoiding the senescence phenotype." (PMID 25613188, 2015). "VHL, MET, folliculin (FLCN), tuberous sclerosis 1 (TSC1), TSC2, fumarate hydratase (FH) and succinate dehydrogenase (SDH) are known as renal cancer genes, and all are involved in pathways that respond to metabolic stress or nutrient stimulation." (PMID 24348776, 2014). "Furthermore, reduction of FH expression is common in renal cancers without FH germline mutations." (PMID 24280230, 2013). "Notably, deletion of fumarate hydratase (FH), an enzyme involved in the TCA cycle, renders renal cancer cells resistant to ferroptosis." (PMID 37794028, 2023). "The diagnostic rate in renal cancer genes was 44.44% (4/9) in syndromic individuals and 2.7% (2/74) in non-syndromic individuals, with pathogenic variants in PTEN and FH in two patients without clinical features of the associated syndromes." (PMID 38002934, 2023). "While loss of the tumor suppressor gene von Hippel Lindau (VHL) is thought to be an initiating event for the majority of RCCs, a role for FH in sporadic renal cancer has not been explored." (PMID 21695080, 2011). "However, mutations in TCA cycle enzymes, such as isocitrate dehydrogenase (IDH1/2), SDH, or fumarate hydratase (FH), generate oncometabolites like D-2-hydroxyglutarate (D-2HG), succinate, and fumarate, which disrupt epigenetic regulation and promote tumorigenesis in gliomas, AML, and renal cancers." (PMID 40734168, 2025).
Uterine leiomyoma (60 papers, 2002 to 2026). The presence of a leiomyoma of the uterus. "We report this unique presentation, highlighting both the unusual molecular findings and the clinical significance of vascular complications in FH-deficient uterine leiomyomas." (PMID 41438660, 2026). "Fumarate hydratase (FH)–deficient uterine leiomyomas are a rare subtype of fibroids with distinctive histological and immunohistochemical features." (PMID 41438660, 2026). "The infrequency of FH-deficient uterine leiomyomas and unique characteristics, such as a genetic link to HLRCC and hereditary leiomyomatosis, already identify the diagnosis and treatment as a unique challenge." (PMID 41585615, 2026). "FH-deficient uterine leiomyomas are a crucial diagnostic consideration in relatively young women presenting with multiple or atypical leiomyomas, enlarged uteri, or a family history suggestive of HLRCC." (PMID 41585615, 2026). "This series demonstrates the consistent under-recognition of FH-deficient uterine leiomyomas in Appalachian women." (PMID 41585615, 2026). "FH-deficient uterine leiomyomas are rare, accounting for approximately 0.4%-1% of all uterine leiomyomas in surgical series." (PMID 41438660, 2026). "We present a case series of three Appalachian women diagnosed with FH-deficient, 2SC-positive uterine leiomyomas, analyzing their presentation, histopathology, and follow-up within the context of regional healthcare disparities." (PMID 41585615, 2026). "Uterine leiomyomas are highly prevalent, yet specific variants, such as fumarate hydratase (FH)-deficient leiomyomas, are rare and clinically significant due to their association with hereditary leiomyomatosis and renal cell carcinoma syndrome (HLRCC)." (PMID 41585615, 2026). "Other research highlights that somatic mutations account for a small but significant percentage of cases: approximately 1–2% of uterine leiomyomas are associated with somatic FH mutations." (PMID 40002168, 2025). "High-intensity focused ultrasound (HIFU) was found to be a feasible treatment option for patients with FH-deficient uterine leiomyomas." (PMID 40002168, 2025). "Studies have shown that somatic mutations in FH are present in a significant portion of uterine leiomyomas, particularly those that exhibit specific histopathological features such as increased cellularity and atypical nuclei." (PMID 40002168, 2025). "Although uterine leiomyomas are the most common benign tumors of the female reproductive system, their fumarate hydratase-deficient variant (dFH-LM) remains one of the most diagnostically challenging subtypes for pathologists." (PMID 41374387, 2025). "Diagnosis of FH-deficient uterine leiomyomas involves a combination of clinical evaluation, imaging, and histopathological examination." (PMID 40002168, 2025). "HLRCC presents with increased cutaneous and uterine leiomyoma, caused by heterozygous pathogenic germline variants in the FH gene." (PMID 38790186, 2024). "At the age of 25, the patient reappeared with symptoms and recurrence, and was diagnosed with uterine leiomyomas (ULMs) of FH mutation and high-grade squamous intraepithelial lesion (HSIL/CIN III) with gland involvement, after complete examination." (PMID 38590329, 2024). "Based on the comprehensive assessment integrating histomorphological and immunohistochemistry findings, we rendered a diagnosis of uterine leiomyomas with strongly suspected FH deficiency." (PMID 38793008, 2024). "Fumarate hydratase-deficient uterine leiomyoma (FH-d UL) is an uncommon subtype among uterine smooth muscle tumors (0.5–2%), showing distinctive histomorphology and FH inactivation." (PMID 38642139, 2024). "Cases presenting with FH germline mutations are often characterized by aggressive RCCs as well as cutaneous and uterine leiomyomas." (PMID 37999735, 2024).
Uterine leiomyoma (continued). "Fumarate hydratase-deficient uterine leiomyoma (FH-d UL) is uncommon and exhibits unique histopathological and molecular changes, representing 0.5–2% of consecutive uterine smooth muscle tumors." (PMID 38642139, 2024). "HLRCC, an autosomal dominant condition caused by germline P/LPvariants in the fumarate hydratase (FH) gene, ischaracterized by multiple cutaneous and uterine leiomyomas andRCC." (PMID 39705504, 2024). "Detection of succinated proteins using the 2SC antibody serves as a biomarker for FH-deficient uterine leiomyomas." (PMID 38793008, 2024). "Hereditary leiomyomatosis and renal cell cancer (HLRCC) is a rare autosomal dominant syndrome caused by a germline mutation in the fumarate hydratase (FH) gene that manifests with cutaneous leiomyomas, uterine fibroids, and renal cell cancer (RCC)." (PMID 39160519, 2024). "Here, we present a case of FH-deficient RCC in a 43-year-old woman with a history of uterine fibroids." (PMID 38974045, 2024). "Fumarate hydratase gene (FH) mutation is characterised by an autosomal dominant disease with increased occurrence of renal tumours, but also by cutaneous (CLs) and uterine leiomyomas (ULs)." (PMID 37606484, 2023). "Fumarate hydratase deficient (FH-d) uterine fibroids are a rare subtype that is diagnosed only on pathologic evaluation." (PMID 37685503, 2023). "Combining these three-patient case studies proves that MED12 and FH mutations co-exist, possibly driving and competing for the same roles in tumorigenesis of uterine fibroid." (PMID 37113812, 2023). "FH mutation found through many genetic expanded carrier screening (ECS) tests has been shown to increase the likelihood of developing uterine fibroids in the heterozygous state." (PMID 37663422, 2023). "Women who are offered genetic screening for infertility treatment should be screened for FH mutations as they are at increased risk of developing uterine fibroids as a part of HLRCC." (PMID 37663422, 2023). "Uterine leiomyomas are characterized by the mutation from fumarate hydratase, one of the enzymes in the Krebs cycle, which catalyzes the hydration of fumarate to malate." (PMID 35163394, 2022). "Here, the FH mutation c.557G>A (p.S186N) was identified in a family with uterine leiomyomas phenotype." (PMID 35163394, 2022). "FH-deficient uterine leiomyomas tumors undergo the impairment of oxidative phosphorylation and metabolic shift to aerobic glycolysis and the increase of HIF-1α, contributing to the oncogenic growth of FH-deficient cells." (PMID 35163394, 2022). "Mutations in FH result in uterine leiomyomas, a rare autosomal dominant inherited metabolic disease." (PMID 35163394, 2022). "In this study, the FH missense mutation c.557G>A (p.S186N) was identified from a Chinese female patient with uterine leiomyomas." (PMID 35163394, 2022). "The result showed that impaired amino acid residue S186 was highly evolutionary conserved among FH proteins from different species, indicating this mutation was likely to be the causative mutation resulting in uterine leiomyomas." (PMID 35163394, 2022). "Our work provides new insight into the FH mutation c.557G>A (p.S186N) underlies uterine leiomyomas and important information for accurate genetic counseling and clinical diagnosis of the disease." (PMID 35163394, 2022). "Based on the combined results of immunohistochemistry and H&E staining, the woman was finally diagnosed with uterine leiomyoma with FH deficiency." (PMID 34889279, 2021). "Germline mutations in FH predispose to dominantly inherited uterine fibroids, skin leiomyomata, and aggressive papillary renal cancer; according to these observations, it was proposed that FH acts as a tumor suppressor." (PMID 32751108, 2020). "Patients with germline mutations in fumarate hydratase (FH) have an increased risk of developing uterine leiomyosarcomas as well as uterine leiomyomas." (PMID 28982163, 2017).